IL1B (interleukin 1 beta)
Diseases named in the same sentence as IL1B in open-access papers (continued):
Sharing a sentence is not in itself a finding about the gene and the disease.
sarcoma (9 papers, 1995 to 2025). A usually aggressive malignant neoplasm of the soft tissue or bone. "Further investigation within the subgroup of OS in sarcoma unveiled a relationship between ZFP36L2 and IL1β, suggesting its potential as a prognostic marker and highlighting the heterogeneity of sarcomas." (PMID 39767767, 2024). "We used a panel of EwS, RMS and OS pediatric sarcoma cell lines to test six cytokines, used for monocyte differentiation and DC maturation (IL-4, GM-CSF, IL-1β, IL-6, TNF and PGE2), for their ability to induce cancer cell immunogenicity and sensitivity to tumor antigen-specific T cells." (PMID 39723214, 2024). "Furthermore, PF-4var but not PF-4 is produced constitutively by smooth muscle cells and by sarcoma cells after induction with cytokines, such as IL-1β and TNF-α, indicating that the regulated expression of these two PF-4 variants is different." (PMID 22384011, 2012). "Applying flow cytometry, immunoblotting, tumor killing and ELISpot assays, we identified TNF and IL-1β to be the strongest inducers of MHC-I, and partly ICAM-1 and CD83 on the majority of pediatric sarcoma cell lines tested." (PMID 39723214, 2024). "Levels of IL-1β, IL-4, IL-6, CXCL5, CXCL12, CXCL14, MIF, IGF-1, TGFβ-1, and CCL21 were increased in one or more sarcoma cohorts compared with controls, and levels of IL-15 and IL-16 were significantly lower in one or more sarcoma cohorts compared to healthy controls." (PMID 41008853, 2025). "IL1β, which is a cytokine primarily released by M1 macrophages, is considered a prognostic marker in many types of cancer, but not in sarcomas." (PMID 39767767, 2024). "In contrast to TNF and IL-1β, the other tested monocyte maturation mediators, including IL-4, GM-CSF, IL-6 and PGE2, weakly affected expression of immunogenic surface markers on pediatric sarcoma cells." (PMID 39723214, 2024). "We observed that TNF and IL-1β upregulated MHC class I, ICAM-1 as well as CD83 and PD-L1 on the surface of pediatric sarcoma cell lines, while IL-4, GM-CSF, IL-6 and PGE2 failed to induce respective effects." (PMID 39723214, 2024). "Thus, we tested TGF-β and IL-1β in HOMC-D4 cells with intermediate morphology and found that they exhibited MMT to the sarcoma type when both factors were added simultaneously but not individually." (PMID 34663305, 2021).
skin aging (9 papers, 2020 to 2025). The gradual irreversible changes in structure of skin that occur as a result of the passage of time.. "Excessive accumulation of inflammatory cytokines such as IL-1β and IL-6 induces inflammatory responses in the skin, accelerating skin aging." (PMID 40136442, 2025). "By week 8, the levels of IL-1β and IL-6 were significantly higher in the HSD group compared to the ND group in this study, indicating that skin aging associated with high salt intake is closely related to inflammation." (PMID 39465002, 2024). "The present in vitro study demonstrated that the hydroalcoholic extract from Sulla coronaria flowers preserves the cellular redox state and counteracts the inflammation response on HDFs induced by IL-1β exposure, thus contributing to the prevention of skin damage and skin aging." (PMID 39409619, 2024). "Future studies should also evaluate the efficacy of chalcone 1 in both in vitro and ex vivo human models of skin aging, focusing on its impact on downstream inflammatory mediators such as PGE2, IL-1β, and IL-6, to further substantiate its potential." (PMID 40710503, 2025). "IL-6, IL-1β, TNF-α and Col-I are the important cytokines in the pathological mechanism of skin aging." (PMID 37927602, 2023).
Ventricular arrhythmia (9 papers, 2018 to 2025). "Studies have demonstrated that elevated TNF-α levels correlate with increased risk of ventricular arrhythmias, while IL-6 and IL-1β promote atrial remodeling, which predisposes individuals to AF." (PMID 40901119, 2025). "Here, we tested whether IL-1β is involved in the ventricular arrhythmias described in CCC." (PMID 36341442, 2022). "Cytokines present in the myocardium, including IL-1β, TNF-α, and IL-6, have even resulted in life-threatening ventricular arrhythmias through modulation of potassium and calcium channels." (PMID 33291425, 2020). "In the control SD rats, there were no obvious ventricular arrhythmias on ECG, the cardiac tissue and mitochondria were basically normal, the serum IL-1β level was low, and the expression of myocardial IL-1β, NLRP3, ROS, p-TAK1, p-p38MAPK and p-NF-κB was weak." (PMID 40146271, 2025).
acute monocytic leukemia (8 papers, 2015 to 2024). Acute monoblastic leukemia (AML-M5), is one of the most common subtypes of acute myeloid leukemia (AML) that is either comprised of more than 80% of monoblasts (AML-M5a) or 30-80% monoblasts with (pro)monocytic differentiation (AML-M5b). "Consistent with our findings, disulfiram has been shown to attenuate IL-1β secretion by acute monocytic leukemia patient-derived human monocytes following LPS priming in vitro." (PMID 37371479, 2023). "Third, the production of CSF3, IL-1β, and IL-6 was evaluated in EV71-infected human acute monocytic leukemia cells (THP-1), differentiated macrophages derived from THP-1 cells (macrophages), and human PBMCs cells." (PMID 28854257, 2017). "We next determined the effects of ANGPTL3 on NF-κB activation in immune cells by knocking down ANGPTL3 in THP1 cells, a human monocyte cell line from acute monocytic leukemia, and confirmed that the knockdown of ANGPTL3 in THP1 cells also potentiated IL-1β-induced transcription of downstream genes." (PMID 37634084, 2024). "Because no cytotoxicity was observed upon treating human acute monocytic leukemia cell line (THP-1) cells with βγ-CAT at concentrations less than 20 nM, 5 nM βγ-CAT was used for the subsequent IL-1β release assay." (PMID 30775460, 2019).
adult-onset Still disease (8 papers, 2011 to 2026). A rare inflammatory multisystem disorder characterized clinically by fever of unknown origin, arthralgia or arthritis, hyperleucocytosis, and typical skin rash. "Interleukin 1β (IL-1β) is emerging as a master mediator of adult onset Still's disease (AOSD) pathogenesis." (PMID 22611515, 2012).
allergic contact dermatitis (8 papers, 2014 to 2025). An inflammatory skin condition caused by an immune response to direct contact between the skin and an allergen. "We previously revealed the similar result that PT attenuates allergic contact dermatitis via inhibition of IL-1β-related NLRP3 inflammasome activation." (PMID 34983566, 2022). "This study aims to investigate the mechanism of calycosin related to tight junctions (TJs) and HIF‐1α both in FITC‐induced mice allergic contact dermatitis and in IL‐1β stimulated HaCaT keratinocytes." (PMID 29993193, 2018). "Moreover, the pronounced suppression of CXCL2 and IL-1β by PjELNs in this study likely accounts for the reduction in neutrophil infiltration, which is a key driver of tissue damage and symptom severity in allergic contact dermatitis." (PMID 41296413, 2025). "The proinflammatory cytokines IL‐1β, TNF‐α, and IL‐6 have been used as biomarkers to investigate periimplant diseases and are also produced in pathological allergic contact dermatitis." (PMID 40730516, 2025). "Allergic contact dermatitis not only elicited more itch- and pain-like behaviors than ICD in mice but also a greater upregulation in the expression of mRNA and protein for IL-1β, TNF-α, CXCL10, and CXCR3." (PMID 31875186, 2019). "In the initiation of allergic contact dermatitis, for example, IL-1β but not IL-1α appears to be important, whereas in irritant contact dermatitis IL-1α appears to play a more important role." (PMID 25371210, 2014).
alopecia areata (8 papers, 2010 to 2025). Loss of scalp and body hair involving microscopically inflammatory patchy areas. "However, numerous studies indicate that alopecia areata is associated with a systemic immune activation and the dysregulation of multiple proinflammatory cytokines, including Interleukin 1 beta (IL-1β), IL-6, tumor necrosis factor alpha (TNF-α), and interferon gamma (IFN-γ)." (PMID 34830700, 2021). "Alopecia areata is also connected with changes in levels of interleukin (IL)-6, tumor necrosis factor-α, IL-1β and Type 17 cytokines." (PMID 38892934, 2024). "Human scalp areas affected by alopecia areata show an excessive expression of IL-1β at the early stages of the disease." (PMID 35625530, 2022). "In human scalp areas affected by alopecia areata, an excessive expression of IL-1β is detected particularly at the early stages of the disease, while susceptibility to the disease and severity are determined by polymorphisms of the IL-1-receptor antagonist and IL-1a." (PMID 20300578, 2010). "Based on these results, we hypothesize that the contact response and disturbed barrier induced by dithranol leads via a vicious loop between AMPs and cytokines such as IL‐1β to an immune suppressive environment in the skin, possibly being beneficial in alopecia areata." (PMID 33629779, 2021). "New drugs could act through modulation of the skin microbiota and/or stimulation of the innate immune response via AMPs such as S100a8/a9 and certain cytokines such as IL‐1β, thereby being potentially beneficial in conditions such as alopecia areata and other cutaneous diseases." (PMID 33629779, 2021). "Indeed, the beneficial effect of dithranol in alopecia areata may be related to modulation of the local microbiota, consistent with the observation that certain bacterial species (such as Corynebacterium) lead to increased IL‐1β and γδT cell expansion in the skin." (PMID 33629779, 2021).
alveolitis (8 papers, 2013 to 2025). "The eight-time exposure of ASD alone (14-week study) deteriorated bronchitis and alveolitis, which accompanied with further increase of cytokines IL-1β, IL-6, IL-12, IL-17A and TNF-α; and chemokines KC, MIP-1α, and RANTES in BALF." (PMID 23731974, 2013). "Infected IL-1β deficient mice also showed perivasculitis, moderate interstitial pneumonia, but no alveolitis." (PMID 40016339, 2025). "Indeed, this herbal medicine can ameliorate pulmonary lesions as it downregulates alveolitis and the Ashcroft score, the underlying mechanism for this might relate to the downregulation of MPO, α-SMA, HYP, collagen I, collagen III, and inflammatory factors (TNF-α, IL-1β, and IL-6)." (PMID 34349830, 2021).
autoimmune hepatitis (8 papers, 2014 to 2025). Hepatitis caused by autoantibodies. "We showed that shikonin can attenuate autoimmune hepatitis caused by ConA through the inhibition of the release of proinflammatory cytokines, such as IL-1β, TNF-α, and IFN-γ." (PMID 27293314, 2016). "The development of autoimmune hepatitis is closely associated with the release of proinflammatory cytokines, including IL-1β, TNF-α, and IFN-γ." (PMID 27293314, 2016). "Several studies show that the release of inflammatory cytokines is involved in autoimmune hepatitis, including IL-1β, TNF-α, IFN-γ, and IL-6, giving rise to the development of liver injury." (PMID 27293314, 2016). "Recent research has shown that autoimmune hepatitis was associated with the release of large amounts of inflammatory cytokines, such as TNF-α, IL-6, IL-1β and IFN-γ, leading to apoptosis and necrosis in liver pathology." (PMID 25761053, 2015). "IL-2, IL-6, TNF-α and IL-1β were released starting at 3h after administration of Con A, and inhibition of the release of these cytokines attenuates the Con A-induced autoimmune hepatitis." (PMID 24498418, 2014). "Similarly, blocking NLRP3 and IL-1β is one of the therapeutic strategies for the treatment of autoimmune hepatitis." (PMID 40367564, 2025). "Pretreatment with ethyl pyruvate ameliorated the pathological effects of Con A-induced autoimmune hepatitis and significantly decreased the levels of TNF-α, IL-2, IL-6 and IL-1β at 3h and 6h and the level of HMGB1 at 6h and 24h post injection." (PMID 24498418, 2014). "Taken together, these results indicated that ethyl pyruvate protected against Con A-induced autoimmune hepatitis by decreasing both early (TNF-α, IL-2, IL-1β and IL-6) and late (HMGB1) cytokine expression in mice." (PMID 24498418, 2014). "The purpose of our study was to determine whether ethyl pyruvate could inhibit the expression and release of both early (TNF-α, IL-2, IL-6, IL-1β) and late (HMGB1 ) cytokines in Con A-induced autoimmune hepatitis." (PMID 24498418, 2014). "In mice with autoimmune hepatitis (AIH), the inhibition of NLRP3 inflammasome-mediated pyroptosis-derived IL-1β led to a decreased accumulation of CD68-positive cells and CD11b-positive cells in liver tissue." (PMID 38380334, 2024).
cerebrovascular disease (8 papers, 2012 to 2023). "Recent studies confirmed that canakinumab specifically reduces IL-1β-mediated inflammatory lesions in cerebrovascular diseases (Luca." (PMID 36238162, 2022).
Chlamydia infection (8 papers, 2011 to 2022). "IL-1β synthesized during early Chlamydia infection was also significantly diminished in TLR3-deficient mice between days 4 and 5, but was virtually identical to wild-type mice after day 5 of infection." (PMID 29624589, 2018). "Consistent in part with this, at 24 h post Chlamydia infection, human iPSdMs were shown, using Luminex bead-based multiplex assays, to express high levels of the pro-inflammatory cytokines IL-6 and TNFα, as well as IL-1β, chemokine IL-8 and the anti-inflammatory cytokine IL-10." (PMID 28440293, 2017).
cholesteatoma (8 papers, 2015 to 2023). A pathologic process characterized by the proliferation of keratinizing squamous epithelium resulting in the accumulation of keratin and cells in the middle ear and/or mastoid. "Cholesteatoma is caused by chronic inflammation of the middle ear, and human cholesteatoma tissue secretes proinflammatory cytokines, such as IL-1β, IL-6, TNF-α, and PGE24,21." (PMID 37537159, 2023). "Moreover, it was demonstrated that the expression of extracellular HMGB1 and DNA fragments in cholesteatoma keratinocytes induce the production of TNF-α and IL-1β, which leads to bone resorption and destruction associated with cholesteatoma." (PMID 37998605, 2023). "In human acquired cholesteatoma, the expression of proinflammatory cytokines (IL-1β, TNF-α and IL-6) and matrix metalloproteinases (MMP-2, MMP-8 and MMP-9) were up-regulated, and their expression levels were positively correlated with TREM-2 expression." (PMID 27934908, 2016). "The expression of the downstream and effector signaling genes TNFα and IL1β was therefore analyzed by QPCR in human samples of cholesteatoma of the middle ear." (PMID 25922834, 2015). "The mRNA expression of TNFα and IL1β was significantly higher in cholesteatoma samples compared to the noninvasive squamous epidermal cells of external auditory skin (EAS)." (PMID 25922834, 2015). "We also confirmed significant upregulation of the downstream effector molecules TNF and IL1β in samples of cholesteatoma compared to samples of the EAS." (PMID 25922834, 2015). "Furthermore, the expression of the pro-inflammatory cytokine IL-1β was significantly higher in acquired cholesteatoma." (PMID 37623440, 2023). "Moreover, the pro-inflammatory cytokines tumor necrosis factor (TNF)-α and IL-1β were up-regulated in acquired cholesteatoma." (PMID 26639190, 2015). "Therefore, it could be inferred that TREM-2 might amplify the inflammatory response in human acquired cholesteatoma and then increase the proinflammatory cytokines levels (IL-1β, TNF-α, and IL-6) while promoting MMP secretion." (PMID 27934908, 2016). "In all analyzed samples, VEGFC and PDGFr, as well as pSTAT3, IL-1β, and TGF-β level expression, were basal in skin tissues with respect to cholesteatoma-related ones." (PMID 37623440, 2023). "In detail the expression of the cytokines, e.g. IL-1α IL-1β and IL-6, TNF-α, GM-CSF and the chemokine IL-8, is elevated in cholesteatoma." (PMID 33627146, 2021). "The scRNA-seq data showed that CD45− cells from cholesteatoma did not exhibit upregulation of IL-1β, PGE2 synthase, or TNF-α, compared to skin fibroblasts." (PMID 37537159, 2023). "Upon LPS challenge, we could detect a significantly higher expression of IL-1α, IL-1β, IL-6 and IL-8 in stem cells and of TNF-a, GM-CSF and CXCL-5 in stem cells and fibroblasts derived from cholesteatoma." (PMID 33627146, 2021). "Indeed, we found a significantly robust upregulation of the proinflammatory-related genes TNFα, IL1β, IRAK1, p65, NOD2, and a downregulation of IKK2 in cholesteatoma." (PMID 25922834, 2015). "The aim of our study was to analyze the expression of inflammatory (IL-1β), hyper-proliferative (STAT-3, TGF-β), and angiogenic (VEGF-C, PDGFr) factors in congenital and acquired cholesteatomas (both in adults and children), which might correlate with the clinical features observed." (PMID 37623440, 2023). "Under standard culture conditions, we detected a tissue-independent higher expression of IL-1β and IL-8 in stem cells, an upregulation of KGF and IGF-2 in both cell types derived from cholesteatoma and higher expression of TLR4 in stem cells derived from cholesteatoma tissue." (PMID 33627146, 2021). "However, the expression and function of TLRs in cholesteatoma remain unclear.We observed inflammatory cell infiltration of the matrix and prematrix of human acquired cholesteatoma, as well as dramatically increased expression of TLR4 and the pro-inflammatory cytokines TNF-α and IL-1β." (PMID 26639190, 2015).
cryptococcosis (8 papers, 2017 to 2025). An acute or chronic, localized or disseminated infection by Cryptococcus neoformans. "Likewise, susceptibility to cryptococcal infection has also been observed in murine knockout models for IL-1β and IL-18 receptors." (PMID 33380899, 2020). "Our observation that both IL-1α and IL-1β were induced in the lungs of BALB/c mice after intratracheal infection with C. neoformans 52D is also consistent with earlier reports that associated the induction of IL-1β in lung and brain with resistance to cryptococcal infection." (PMID 29403476, 2017). "While most studies have shown that IL-18 is important during cryptococcosis, IL-1β itself is sometimes depicted as unnecessary for host protection." (PMID 33380899, 2020). "Interleukin-1 alpha (IL-1α) and interleukin-1 beta (IL-1β) are pro-inflammatory cytokines that are induced after Cryptococcus neoformans infection and activate the interleukin-1 receptor type I (IL-1RI)." (PMID 29403476, 2017). "Since IL-1β levels and the expression of its receptor (Il1rn) are high in H99-infected brains, it is probable that reduction in Lcn2 antagonizes the effects of this pro-inflammatory cytokine and serves as a protective mechanism to mitigate brain tissue damage during cryptococcosis." (PMID 40038673, 2025). "To test this, we quantified levels of seven cytokines and chemokines (interferon-γ (IFN-γ), TNF-α, interleukin-1b (IL-1b), interleukin-6 (IL-6), MCP-1, G-CSF and GM-CSF) in the media immediately following cryptococcal infection and again 18 hours later." (PMID 29596441, 2018).